CD44 (CD44 molecule (IN blood group))
Diseases named in the same sentence as CD44 in open-access papers (continued):
Sharing a sentence is not in itself a finding about the gene and the disease.
breast carcinoma (continued). "Interestingly, CD44s was reported to inhibit breast cancer stemness, while the cleaved product of CD44 was reported to contribute to breast cancer stemness." (PMID 38783892, 2024). "CD44 is essential for normal stem cell maintenance and homing, and is a distinguishing feature of cancer stem cells (CSCs) in various cancers including lung, melanoma, leukemia, and breast cancers." (PMID 39184916, 2024). "Interestingly, rhPRG4 reduced the TGFβ-induced increase in the CD44 protein level, thus, reducing the invasiveness of breast cancer HCC38 cells." (PMID 38612911, 2024). "Finally, the anticancer efficacy of free Cro and Cro-loaded in this Cd-NC was studied and compared in a panel of breast cancer cell lines with different degrees of CD44 cell surface receptor." (PMID 38966182, 2024). "In this regard, EVs produced by breast cancer cells treated with doxorubicin could spread resistance to this chemotherapeutic drug via the intercellular transfer of CD44." (PMID 38542421, 2024). "Several groups had focused on PD-L1 inhibitor delivery to CD44+ breast cancer cells." (PMID 38609981, 2024). "Moreover, the combination of CD44+/CD24− also marks CSCs in breast cancer, prostate cancer, head and neck squamous cell carcinoma, and ovarian cancer." (PMID 38965243, 2024). "The subpopulation of breast cancer cells with high level of stem cell markers (CD44, ALDH1, CD133, OCT4, SOX2 and Nanog) exhibit the capacities of self-renewal and multi-directional differentiation, playing critical roles in tumor initiation, therapeutic resistance, relapse, and metastasis." (PMID 38523299, 2024). "Such an association between hypoxia and CD44 induction is supported by previous studies that demonstrated HIF‐1α transcriptional activation of CD44 in nucleus pulposus cells and co‐localization of hypoxia and CD44 expression in breast cancer xenografts." (PMID 37849446, 2024). "We speculate that patient‐derived TCs might compensate for the blockade of CD44 by over‐expressing other HA‐binding receptors such as CD168, which is associated with breast cancer invasion." (PMID 39041892, 2024). "It is well-appreciated that TGFβ can increase CD44 expression in breast cancer cells through EMT." (PMID 38612911, 2024). "This subpopulation of breast cancer cells (CD44+/CD24−) has stem/progenitor cell properties." (PMID 39469631, 2024). "These breast cancer cell lines contain CD44 as a surface receptor." (PMID 38966182, 2024). "Additionally, the levels of ALDH and CD24−/CD44+/EpCAM+ cancer stem cell-like cell markers increased in breast cancer cells after chemotherapy, which helped cancer cells resist chemotherapy drugs and increase their stemness at the level of cell transcription." (PMID 38540708, 2024). "Additionally, recent studies have identified a highly potent small‐molecule antagonist of exportin‐1, which selectively eliminates CD44+CD24− enriched breast cancer stem‐like cells." (PMID 38982317, 2024). "Several reports suggest that the development of resistance to doxorubicin involves cancer cells that acquire multidrug-resistant phenotypes, populations (CD44+/CD24 −/low) of breast cancer stem cells (CSCs), and initiation of the epithelial-mesenchymal transition (EMT)." (PMID 39180549, 2024). "Histopathological analysis of mice tumor sections revealed a higher accumulation of necrotic debris correlating with the higher tumorigenic potential of the CD24−/CD44+‐breast CSCs as compared with CD24+‐breast cancer cells xenotransplanted groups, which was quantified using Image J software." (PMID 38522013, 2024). "Based on CD44 expression, CSCs in breast cancer were demonstrated." (PMID 39335624, 2024). "CD44 was involved in the chemokine signaling pathway, Fc receptor-mediated phagocytosis, natural killer (NK) cell-mediated cytotoxicity, and T cell receptor signaling pathway in breast cancer." (PMID 38590654, 2024). "Compelling evidence further suggests that the splicing switch of CD44 may play inverse roles in breast cancer." (PMID 38783892, 2024).
breast carcinoma (continued). "Furthermore, cancer cells serve as major recipients for the released iron, facilitated by the upregulation of CD44—a consistent finding across both tested breast cancer cell lines and human breast cancer patients from the TCGA database." (PMID 39201626, 2024). "Furthermore, recent research has shed light on the roles of both ALDH1 and CD44 as indicators of breast cancer malignancy, highlighting their distinct functions in tumorigenesis and progression." (PMID 38719848, 2024). "For instance, in ovarian cancer and breast cancer cells, HA interacts with CD44 to promoting the formation of a complex between CD44, Nanog, and STAT‐3, which in turn induces the expression of SOX2, REX1, and MDR1, enhancing thus resistance to doxorubicin and paclitaxel." (PMID 37953485, 2024). "Similarly, the expression of CD44 in fibroblasts supports the survival and resistance of breast cancer cells to paclitaxel through IGF2BP3-CD44-IGF2 signaling axis." (PMID 38796656, 2024). "Similarly, a significant increase in the colocalization of GFP and p‐EGFR (activated EGFR) was observed in the CD24−/CD44+‐breast CSC as compared with the CD24+‐breast cancer cell xenotransplanted groups." (PMID 38522013, 2024). "In addition, RHAMM interacts with CD44 to activate ERK1/2 in breast cancer cell lines, and CD44 is reported to upregulate MDR1 microRNA-21 (miR-21), resulting in MDR1 (multi drug resistance protein 1) or anti-apoptotic protein Bcl2 in breast cancer cells." (PMID 39518040, 2024). "Interestingly, recent evidence demonstrated that RHAMM is more sensitive to the density of HA than CD44 in breast cancer cell lines, and its surface expression can be enhanced to compensate the pro‐tumorigenic signaling mediated by CD44 when CD44 is blocked." (PMID 37953485, 2024). "Additionally, CD44-expressing breast cancer cells exhibit stem-cell-like characteristics and indicate a poor prognosis when detected within the bone marrow of patients with early-stage breast cancer." (PMID 39430073, 2024). "Furthermore, secreted RHAMM has the capability to bind with HA and, in conjunction with CD44, promotes the invasiveness of breast cancer cells." (PMID 38791985, 2024). "Thus, in the next step, the anticancer effect of Cro carried by this nanocarrier was studied and compared with the free Cro in a panel of breast cancer cells with different amounts of CD44, a steroid hormone receptor, on the cell surface." (PMID 38966182, 2024). "Furthermore, p27CK-DD expression in MCF12A causes a shift from predominantly CD44low/CD24+ to a greater population expressing stem cell surface markers, CD44+CD24low/-, a hall mark of breast cancer initiating cells or CSCs2." (PMID 38886396, 2024). "rhPRG4 has shown success in preserving joint health in vivo in osteoarthritis models, and a recent study demonstrated that it can also suppress transforming growth factor beta (TGFβ)-induced migration and invasion in breast cancer cells by reducing CD44 protein levels." (PMID 38612911, 2024). "Notably, the phenotype of breast cancer CSCs, characterized by the expression markers CD44+/CD24−/low and their ability to form mammospheres in culture, sets them apart as targets for therapeutic intervention." (PMID 38730626, 2024). "However, prolactin stimulation in both mammary cancer cell lines significantly increases labile iron pools via the upregulation of CD44." (PMID 39201626, 2024). "Additionally, CD44-mediated cell aggregation through CD44–CD44 homophilic protein interactions was reported in vitro in MDA-MB-231 breast cancer cells." (PMID 39273689, 2024). "The presence of CD44+ CTC clusters correlates with a poor prognosis in breast cancer patients." (PMID 37866630, 2023). "In summary, CD44 is often used as a marker for CSCs, particularly in breast cancer and in head and neck cancer, because CD44-positive cells are associated with properties that are often attributed to CSCs, such as self-renewal and tumor-initiating capabilities." (PMID 37958796, 2023).
breast carcinoma (continued). "Furthermore, after undergoing standard chemotherapy treatment with docetaxel, doxorubicin, cyclophosphamide and trastuzumab, breast cancer cells that are CD44+ and CD24- were found to exhibit resistance to chemotherapy." (PMID 37886168, 2023). "Given that CD44 is a well-known marker in breast cancer stem cells (BCSCs), the influence of TDP-43 on CD44 alternative splicing may accelerate cancer progression." (PMID 37996849, 2023). "Additionally, breast cancer cases exhibiting the CD44+/CD24−/low phenotype display poor prognosis and limited response to chemotherapy." (PMID 38313430, 2023). "MDA‐MB‐231 cells express high levels of the mesenchymal marker CD44 and intermediate levels of the epithelial marker CD24, a phenotype early on linked to high tumor‐initiating (or cancer stem cell) ability of patient‐derived breast cancer xenografts." (PMID 37518985, 2023). "Considering our previous findings that NETs increase gene expression of ZEB1 and CD44 in MCF7 breast cancer cells, we hypothesized that NETs could induce EMT activation through TF upregulation." (PMID 38201433, 2023). "Moreover, aldehyde dehydrogenase (ALDH) activity is recognized as a biomarker of breast cancer stem cells with a CD44+/CD24− phenotype." (PMID 36768815, 2023). "CD44 is one of the cell surface adhesion receptors for extracellular matrix proteins, including hyaluronic acid (HA), and is also a known cancer stem cell marker in breast cancer." (PMID 37064130, 2023). "We found that plasma ofCS-modified CD44 level was significantly associated with progressive pathologic TNM stage in some cancers, such as breast cancer (BRCA), lung cancer (LC), and liver hepatocellular carcinoma (HCC), indicating its’ prognostic significance of cancer detection." (PMID 36746966, 2023). "In solid tumor CSCs of breast cancer, a CD44+/CD24− phenotype has been identified." (PMID 38313430, 2023). "It is well known that HAS2 promotes breast cancer cell invasion through the CD44 pathway." (PMID 37064130, 2023). "This CD44+CD24−/low breast cancer cells phenotype was highly resistant to lapatinib." (PMID 36768445, 2023). "Additionally, MCF7 human breast cancer cells had similar results, and cells cultured in gel with modulus of 5.3 kPa showed the highest CD44 expression and the largest tumor spheres." (PMID 37468874, 2023). "More recently, it was observed that the transmembrane glycoprotein CD44, a cancer stem cell (CSC) marker, which is also associated with EMT, regulates the expression of TF in breast cancer cells, resulting in enhanced tumor cell procoagulant activity and metastatic dissemination." (PMID 38201433, 2023). "In addition, MARCHF8 overexpression also promotes apoptosis and hinders tumorigenesis and metastasis of breast cancer cells by downregulating CD44 and STAT3." (PMID 36867660, 2023). "Breast cancer cells with the CD44+/CD24− phenotype were enriched for tumor-initiating CSCs and were highly invasive, and the prevalence of CD44+/CD24− tumor cells in breast cancer may favor distant metastasis." (PMID 37377604, 2023). "Mariotto and her colleagues established an in vitro hypoxia-resistant breast cancer model and demonstrated that cycling hypoxic/re-oxygenation stress selected out a CD44+CD24−ESA+ subpopulation with sphere-forming capacity, which was sufficiently identified as BCSCs." (PMID 36768876, 2023). "CD44 is a cell surface receptor that is overexpressed in breast cancer, and targeting this receptor could facilitate intracellular uptake of nanoparticles, thereby increasing drug concentrations in cancer cells through CD44 receptor-mediated endocytosis." (PMID 36850308, 2023). "Additionally, TNF-α is known to regulate CD44 and its isoform expression in different breast cancer cell lines via a different pathway to promote cell migration." (PMID 36979874, 2023). "Moreover, in breast cancer stem cells, hypoxic CAFs release exosomes to transfer circHIF1A, which regulates miR-580-5p by sponging CD44 expression." (PMID 37496657, 2023).
breast carcinoma (continued). "Sialofucosylated glycoforms of CD44 have been shown to act as shear-resistant ligands for E-selectin in breast cancer cell adhesion to the endothelium, colon cancer cell lines as well as prostate cancer cell lines, but not yet on lung cancer cell lines to the best of our knowledge." (PMID 37399498, 2023). "Up‐regulation of CD44, according to immunohistological research, influences the pace of cell invasion, tumor growth, and metastasis in a variety of malignancies, including breast cancer." (PMID 36289579, 2023). "Moreover, the CD44+/CD24− breast cancer cell subpopulation, typically identified as cancer stem cells, is associated with invasive properties and a poor prognosis." (PMID 37568628, 2023). "Evidence has confirmed that lamellipodia formation could be regulated by various adhesion molecules, such as CD44, and we previously reported that lamellipodia at the leading edge of luminal type breast cancer (BrCa) were enriched with high expression of CD44." (PMID 37842093, 2023). "CD44 is an integral transmembrane protein expressed in breast cancer cells in various isoforms." (PMID 37175137, 2023). "An overexpression of hnRNPM in MCF-7 human breast cancer cells resulted in a decreased expression in CD44 isoforms containing exon v6 and an increased expression in CD44 isoform 4 with a slight change in the total level of CD44 transcripts." (PMID 38106992, 2023). "Notably, an elevated expression of TK1, CDK9, and CD44 within plasma exosomes from drug-resistant breast cancer patients correlates with therapy resistance." (PMID 38001753, 2023). "Importantly, the presence of CD44+ CTC clusters correlates with a poor prognosis in breast cancer patients." (PMID 36824757, 2023). "The silencing of STAT3 by shRNA in HER2 overexpressing breast cancer cells resulted in a reduction in CD44-positive cells and the downregulation of the expression of stem cell markers, such as Octamer-binding transcription factor (OCT-4) and SRY (sex determining region Y)-box 2 (SOX-2)." (PMID 38067351, 2023). "Moreover, we have previously shown a correlation between CD44 and membrane fluidity in breast cancer cells." (PMID 37399498, 2023). "Panobinostat accelerated the expression of APCL and blocked Wnt/β-catenin pathway via promotion of β-catenin degradation in breast cancer, resulting in inactivation of β-catenin targets, including c-Myc, CD44, Cyclin D1 and c-Jun, which contributed to inhibition of tumor growth and metastasis." (PMID 36969235, 2023). "For example, it has been proven that quercetin suppressed the activation of PI3K and AKT, which increased the ratio of BAX/Bcl-2 to induce apoptosis of breast cancer cells, as well as significantly inhibiting the growth and metastasis of CD44+/CD24 breast cancer stem cells in vivo." (PMID 36900408, 2023). "The CD44 protein expression in breast cancer tissues was detected using immunohistochemistry." (PMID 36964570, 2023). "In addition, increasing the secretion of soluble CD44 in lung metastases of breast cancer can stimulate the interstitial tissue to produce a large amount of HMW-HA, forming a physical barrier and inhibiting the colonization of metastatic cells." (PMID 36698043, 2023). "Therefore, this study aimed to improve the anticancer effect of CME on breast cancer cells by CD44-targeted nanoparticles." (PMID 37376218, 2023). "In breast cancer, they are detected by CD44+/CD24−/low phenotype." (PMID 37492743, 2023). "Furthermore, improved magnetic resonance imaging (MRI) and photothermal ablation, both in vitro and in vivo, demonstrated substantial photothermal effects specifically targeting CD44 HA receptor-overexpressing breast cancer." (PMID 37376161, 2023).
breast carcinoma (continued). "Interestingly, another group found miR-200 to be down-regulated in BCSCs (CD44+/CD24−/low) derived from human breast cancer samples." (PMID 37374142, 2023). "Indeed, the CD44+/CD24-/low CSC phenotype is associated with the expression oh HIF-1α and poor survival of patients with breast cancer." (PMID 37064130, 2023). "The resultant sensor could determine CD44 with a detection limit of 2.17 pg mL−1 and CD44 positive breast cancer cells at a limit of 8 cells mL−1." (PMID 37998127, 2023). "Therefore, specific targeting of CD44 in breast cancer with monoclonal antibodies, small molecule inhibitors, or siRNA and RNA interference, are possible targeting options." (PMID 37626666, 2023). "Moreover, recent studies suggest that CD24 + /CD49f + murine breast cancer cells and CD24-/CD44 + human breast cancer cells exhibit stem cell properties, also known as breast cancer stem cells or breast cancer stem-like cells." (PMID 38031089, 2023). "However, the percentage of CD44+-stained mammary tumor cells of MT-Zn NPs group was significantly lower than that of MT-Fu group, p < 0.05." (PMID 36864097, 2023). "In the murine 4T1 breast cancer cell line, cells expressing the CD44v8-10 alternative isoform including the variable portion of exon 8 to 10 were found to have a higher metastatic potential than those only expressing the standard form of CD44." (PMID 35406498, 2022). "This change in morphology and protein expression pattern is associated with an acquisitionof breast cancer stem cell marker proteins ALDH-1 and CD44+/CD24−/low, which may play distinct functional roles in metaplastic carcinomas." (PMID 36092916, 2022). "More interestingly, HA specifically binds to CD44 and improves intracellular anticancer drug delivery to various cancerous cells, including breast cancer cells; therefore, HA-containing systems can act as favorable anticancer drug carriers for effective chemotherapy [14,18,22,]." (PMID 35875198, 2022). "Furthermore, these cryogels would help us investigate the role of CD44/HA-mediated signaling in mammary carcinoma progression and metastasis." (PMID 35198956, 2022). "In vivo evidence proved that CD44 induces breast cancer metastasis to the liver." (PMID 35875198, 2022). "Additionally, a dual-targeting platform for CD44 has already been tested in hepatic tumors (e.g., HA- glycyrrhetinic acid -conjugated polymer to target liver) and breast cancer (e.g., HA-folic acid micelles for cells overexpressing the folic acid receptor)." (PMID 35785191, 2022). "In addition, MCT1 was reported to have tumorigenic and metastatic activity and to co-localize with CD44 in breast cancer and metastatic prostate cancer cells." (PMID 36302783, 2022). "We hypothesized that macroporous HA-based cryogels could provide CD44-positive breast cancer MCTS with robust physical support, allowing simultaneous cell-cell and cell-ECM interactions." (PMID 35198956, 2022). "Binding to the GC-rich structural domain of CD44, HnRNPM promotes the skipping of exon 8, which ultimately promotes breast cancer metastasis by enhancing TGFβ signaling and thus activating the switch of alternative splicing that occurs during epithelial-mesenchymal transition (EMT)." (PMID 36052258, 2022). "Therefore, the use of Sibilin, Zerumbone, or curcumin/epigallocatechin notably reduced the population of CD44+ tumor cells (breast cancer, pancreatic cancer, and prostate cancer), suggesting a novel approach for the treatment of sarcomas." (PMID 35785191, 2022). "Subsequently, the expression of CD44 was investigated in different breast cancer cell lines." (PMID 36289750, 2022). "Notably, current literature has suggested the critical role of RUNX2 for malignant progression of breast cancer by modulating the CD44 +/CD24- breast cancer stem cells." (PMID 36483054, 2022).